ANGPTL8 (angiopoietin like 8)
Diseases named in the same sentence as ANGPTL8 in open-access papers (continued):
Sharing a sentence is not in itself a finding about the gene and the disease.
tumor (6 papers, 2021 to 2026). "Furthermore, we demonstrated that ANGPTL8 inhibited macrophage polarization into the M1 phenotype and coordinately regulated tumor-associated T cell function to form an immunosuppressive microenvironment, leading to the escape of tumorigenic HCC cells from immune surveillance." (PMID 37188659, 2023). "ANGPTL8 significantly augments lipid synthesis within HCC cells and promotes tumour growth and metastasis by modulating the immune response within the tumour microenvironment; therefore, it was named “tumour-derived factor 26” (TD26)." (PMID 38107478, 2023). "We assessed the role of ANGPTL8, a protein secreted by HCC cells, in hepatocarcinogenesis and the mechanisms through which ANGPTL8 mediates crosstalk between HCC cells and tumor-associated macrophages." (PMID 37188659, 2023). "ANGPTL8 expression was positively correlated with tumor malignancy in HCC, and high ANGPTL8 expression was associated with poor overall survival (OS) and disease-free survival (DFS)." (PMID 37188659, 2023). "Our data support the notion that ANGPTL8 has a dual role in promoting tumor cell proliferation and immune escape during hepatocarcinogenesis." (PMID 37188659, 2023). "Our data support that ANGPTL8 has a dual role in promoting tumor cell proliferation and immune escape during hepatocarcinogenesis." (PMID 37188659, 2023). "With the deepening of research, evolving implications of ANGPTL8 actions in the regulation of inflammation, tumours, circulatory system-related diseases, and ectopic lipid deposition have been reported." (PMID 38107478, 2023). "The ability to escape immune surveillance is critical for tumor development, and our RNA-seq results showed that ANGPTL8 modulates genes involved in the immune response in DEN-induced mouse liver tumors." (PMID 37188659, 2023). "ANGPTL3, ANGPTL4, ANGPTL5, ANGPTL7, and ANGPTL8 were significantly hypermethylated in tumor tissues." (PMID 35692877, 2022). "In contrast, the DNA methylation levels of ANGPTL2, ANGPTL7, and ANGPTL8 were significantly positively correlated with tumor grade, and the DNA methylation levels of ANGPTL3, ANGPTL5, and ANGPTL7 were significantly negatively correlated with age." (PMID 35692877, 2022). "Significant differences in protein expression levels of ANGPTL8/betatrophin were found in ccRCC/KIRC between tumor and normal samples." (PMID 34646087, 2021). "Hepatokines, particularly fibroblast growth factor 21 (FGF21), emerge as key mediators of tumor progression and potential biomarkers of metabolic vulnerability, while Fetuin-A and angiopoietin-like protein 8 (ANGPTL8) further support the liver's endocrine role in oncogenic signaling." (PMID 42278446, 2026). "To understand how ANGPTL8 might affect early tumor development, we evaluated different models of hepatocarcinogenesis." (PMID 37188659, 2023). "In summary, the potential role of ANGPTL8 in tumours may be complicated and involve multiple pathways." (PMID 38107478, 2023). "ANGPTL8 expression was significantly increased in tumor tissue compared to normal tissue." (PMID 37188659, 2023). "ANGPTL8 may be induced by STAT3 signalling, FFAs or other proinflammatory cytokines, such as TNF-α and TGFβ1, in the tumour microenvironment, and it may affect the differentiation and development of tumours through the following pathways." (PMID 38107478, 2023). "Second, ANGPTL8 could also interact with PIRB in macrophages (Kupffer cells) to upregulate Fgr expression and drive macrophage polarization into the M2 phenotype to suppress anti-tumor immune responses by increasing the number of CD4+FOXP3+ and CD8+PD-1+ T cells in the tumor microenvironment." (PMID 37188659, 2023).
infection (3 papers, 2017 to 2024). The state of being infected such as from the introduction of a foreign agent such as serum, vaccine, antigenic substance or organism. "Taken together, these data indicate that LPS can upregulate the expression of ANGPTL8 both in vivo and in vitro, suggesting that ANGPTL8 may participate in the pathological progression of liver injury caused by infection." (PMID 39019343, 2024). "However, a significant decrease in the expression of ANGPTL8 24 h after LPS injection was observed in our study, which may be due to the metabolic response to starvation caused by acute infection." (PMID 39019343, 2024). "To clarify the mechanism by which ANGPTL8 regulates liver lipid metabolism during infection, we performed RNA-seq analysis of livers dissected from LPS-challenged WT mice and ANGPTL8 KO mice." (PMID 39019343, 2024). "PirB blockade with neutralizing antibodies or PirB knockdown through lentiviral infection abrogates the effects of ANGPTL8-induced phosphorylation of ERK1/2, P38, and AKT, suggesting that ANGPTL8-responsive signals are downstreams of PirB." (PMID 37481670, 2023). "Here we found that the level of circulating ANGPTL8 was dramatically increased in severe infection." (PMID 29255244, 2017). "First, p62 and many other chaperones are stress-responsive, possibly to ensure different substrates are properly degraded under certain conditions; similarly, ANGPTL8 is a stress-responsive molecule with enhanced expression under TNFα, IL-1β, LPS, or infection." (PMID 29255244, 2017).
infectious disease (3 papers, 2017 to 2022). A disorder directly resulting from the presence and activity of a microbial, viral, or parasitic agent in humans. "Circulating ANGPTL8 was not only enhanced in patients with infectious disease, but ANGPTL8 mRNA was also expressed at high levels in mice treated with LPS, acting as a “brake” for inflammation." (PMID 35851270, 2022). "Consistently, in patients diagnosed with infectious diseases, enhanced circulating ANGPTL8 levels were detected." (PMID 31225468, 2018). "In vivo, circulating ANGPTL8 level is high in patients diagnosed with infectious diseases, and the ANGPTL8/p62-IKKγ axis is responsive to inflammatory stimuli in the liver of LPS-injected mice." (PMID 29255244, 2017). "We also noted markedly enhanced circulating ANGPTL8 in the patients with infectious disease." (PMID 31225468, 2018).
retinopathy (3 papers, 2021 to 2025). "Paradoxically, the results of another prospective study showed that the baseline ANGPTL8 level was positively correlated with the risk of retinopathy and all-cause mortality in patients with T2DM." (PMID 34582711, 2021). "Many studies have shown that ANGPTL8 can be used as a bio-marker of these metabolic disorders related diseases, and the baseline ANGPTL8 level has also been found to be positively correlated with retinopathy and all-cause mortality in patients with T2DM." (PMID 34582711, 2021). "Although current studies suggest that ANGPTL8 may be a harmful molecule; that is, elevated baseline ANGPTL8 levels are associated with a higher risk of retinopathy and all-cause mortality in patients with T2DM." (PMID 34582711, 2021).
cardiac disease (1 paper, 2022). "Thus, regarding the action of ANGPTL8 on metabolic-cardiac disease, further work is needed to fully understand its mechanism of action." (PMID 35851270, 2022).
inflammation (1 paper, 2025). Aberrant reaction of the microcirculation characterized by movement of fluid and leukocytes from the blood into extravascular tissues. "The reduction in ANGPTL8 levels could indicate altered lipid metabolism, where LPL activity is deregulated, leading to an accumulation of free fatty acids and exacerbating pancreatic inflammation." (PMID 40282999, 2025).
ANGPTL8 also shares sentences with these, for which no sentence is quoted: Hypercholesterolemia (4 papers); liver disease (4); arteriosclerosis (2); central obesity (2); diabetic retinopathy (2); glioblastoma (2); glucose metabolic disorders (2); lung squamous cell carcinoma (2); Prader-Willi syndrome (2); abdominal aortic aneurysm (1); acute coronary syndrome (1); acute pancreatitis (1); albuminuria (1); bacterial infection (1); bladder urothelial carcinoma (1); breast carcinoma (1); cervical cancer (1); cholangiocarcinoma (1); Cognitive impairment (1); Crohn disease (1); degeneration disc (1); dermatosis (1); end-stage renal disease (1); fibrosis (1); Genetic obesity (1); glomerulosclerosis (1); head and neck cancer (1); heart failure (1); insulin-resistant diabetes (1); large intestine cancer (1).
A further 17 diseases each share a sentence with ANGPTL8 in 1 paper.